PCAT14 (prostate cancer associated transcript 14)
Gene: Long non-coding RNA gene on chromosome 22 (23,536,821 to 23,547,797, forward strand). Ensembl gene ENSG00000280623.
Diseases named in the same sentence as PCAT14 in open-access papers:
PCAT14 is named in the same sentence as 8 diseases in open-access papers, as found by Europe PMC text mining. Sharing a sentence is not in itself a finding about the gene and the disease. The quoted sentences say what the papers report.
prostate carcinoma (13 papers, 2017 to 2025). A carcinoma that arises from epithelial cells of the prostate gland. "The expression of PCAT14 was independently associated with the progression-free interval in prostate cancer patients." (PMID 35003397, 2021). "The ROC curve showed that PCAT14 had a significant diagnostic ability (area under curve = 0.818) for prostate cancer." (PMID 35003397, 2021). "Receiver operating characteristic (ROC) curves were used to evaluate the value of PCAT14 as a diagnostic marker for prostate cancer." (PMID 35003397, 2021). "Down-regulation of PCAT-14 in prostate cancer has been associated with an increased probability of metastatic progression and mortality across multiple independent datasets and ethnicities." (PMID 28415780, 2017). "This study showed that PCAT14 has significant diagnostic ability in prostate cancer and might be expected to become an effective screening and diagnostic marker for prostate cancer." (PMID 35003397, 2021). "Interestingly, 14 unique HERVK peptides mapped to a single variant hPSC-enriched isoform of the PCAT14 gene (prostate cancer-associated transcript 14) that has hitherto been considered noncoding." (PMID 34390351, 2021). "Still, few studies have reported the association between PCAT14 and prostate cancer." (PMID 35003397, 2021). "This study performed a detailed comparative analysis of lncRNA PCAT14 and prostate cancer-related clinical indicators (age, race, diagnostic validity, tumor-node-metastasis (TNM) staging, initial treatment outcome, residual tumor, PSA, Gleason score, and overall survival)." (PMID 35003397, 2021). "PCAT14 is highly expressed in prostate cancer and is expected to be a diagnostic marker." (PMID 35003397, 2021). "PCAT-14 (Prostate Cancer Associated Transcript-14) is a prostate cancer-specific lncRNA." (PMID 29755696, 2018). "Besides, decreased expression level of prostate cancer associated transcript-14 (PCAT-14) was prognostic for the metastatic disease and poor survival for patients with prostate cancer." (PMID 28915709, 2017). "Moreover, PCAT14 has been associated with the hormone testosterone in prostate cancer." (PMID 36617651, 2022). "Studies in two separate independent cohorts validated prostate cancer-associated transcript-14 (PCAT-14), an androgen-regulated lncRNA, might be used as a novel PCa diagnosis biomarker for its high expression prostate tumors and low expression linked to poor outcomes." (PMID 36514044, 2022). "PCAT14 might be promising as a diagnostic marker for prostate cancer." (PMID 35003397, 2021). "These include genes such as DANCR, DRAIC, PCAT29, PCAT19, and PCAT14, all of which have been shown to be regulated by the AR, and are important regulators of prostate cancer cell proliferation, division, migration, and invasion." (PMID 38396008, 2024). "At the same time, PCAT14 has been characterized as a novel prostate cancer and lineage-specific lncRNA." (PMID 36338971, 2022). "We analyzed the relationship between PCAT14 expression and immune cell infiltration in prostate cancer using SSGSEA." (PMID 35003397, 2021). "The relationship between PCAT14 and immune cell infiltration was analyzed to explore the effect of PCAT14 on the immune-related functions of prostate cancer." (PMID 35003397, 2021). "This study first analyzed the expression of the lncRNA PCAT14 in prostate cancer and its relationship with prostate cancer prognosis." (PMID 35003397, 2021). "A reduced expression of PCAT14 in prostate cancer was related to T stage, N stage, primary therapy outcome, residual tumor, Gleason score, and age." (PMID 35003397, 2021). "This study provides a scientific basis for further research on the pathogenesis of the lncRNA PCAT14 in prostate cancer." (PMID 35003397, 2021). "The highlight of our study was to reveal the relationship between PCAT14 expression and a variety of immune cells infiltrating prostate cancer." (PMID 35003397, 2021).
prostate carcinoma (continued). "At present, the relationship between PCAT14 and immune cell infiltration in prostate cancer is still unclear." (PMID 35003397, 2021). "A detailed comparative analysis was conducted to analyze the correlation between PCAT14 and prostate cancer disease progression." (PMID 35003397, 2021). "A reduced expression of PCAT14 in prostate cancer was related to T stage (P = 0.005), N stage (P = 0.009), primary therapy outcome (P = 0.022), residual tumor (P < 0.001), Gleason score (P < 0.001), and age (P = 0.020)." (PMID 35003397, 2021). "Our results showed that the expression of PCAT14 was negatively correlated with the infiltration level of pDC, aDC, Tregs, and neutrophils in prostate cancer." (PMID 35003397, 2021). "This research also found that the expression of PCAT14 is negatively correlated with the infiltration of pDC, aDC, Tregs, and neutrophils in the tumor microenvironment of prostate cancer." (PMID 35003397, 2021). "The relationship between PCAT14 expression and the clinicopathological characteristics of prostate cancer was analyzed based on The Cancer Genome Atlas (TCGA) database." (PMID 35003397, 2021). "According to the average relative expression level of PCAT14, prostate cancer patients were divided into two groups: the high PCAT14 expression group (n = 250) and the low PCAT14 expression group (n = 249)." (PMID 35003397, 2021). "We also analyzed the expression of PCAT14 in 52 prostate cancer tissues and their matched adjacent tissues." (PMID 35003397, 2021). "The area under the curve (AUC) of PCAT14 was 0.818, indicating that PCAT14 can be used as an ideal biomarker for diagnosing prostate cancer." (PMID 35003397, 2021). "We analyzed the expression of PCAT14 in 499 prostate cancer samples and 52 adjacent normal tissue samples, and the results showed that PCAT14 was highly expressed in prostate cancer tissues." (PMID 35003397, 2021). "Still, there are few reports on the association between PCAT14 and prostate cancer, the relationship between PCAT14 and the clinical indicators of prostate cancer, and the relationship between PCAT14 and immune cell infiltration in prostate cancer." (PMID 35003397, 2021). "In-vitro data confirmed that low PCAT-14 expression increases migration of prostate cancer cells, while overexpression of PCAT-14 reduces their growth, migration, and invasion." (PMID 28415780, 2017). "For example, we found the pca-lncRNAs SCHLAP1 and PCAT14, both known to be enriched in prostate cancer cells, to exhibit upregulation (logFC = 1.28, FDR = 1.63 × 10−2) and downregulation (logFC = −3.77, FDR = 1.83 × 10−20), respectively, in metastases compared to primary tumors." (PMID 38396008, 2024). "Since dendritic cells (DC) and neutrophils mainly play an antitumor role in the tumor microenvironment, PCAT14 might promote the progression of prostate cancer by inhibiting the antitumor effect of DC and neutrophils." (PMID 35003397, 2021). "Therefore, this study is aimed at investigating the relationship between the LncRNA PCAT14 and the clinical characteristics of prostate cancer and immune cell infiltration." (PMID 35003397, 2021). "The results also showed that PCAT14 was highly expressed in prostate cancer tissues." (PMID 35003397, 2021). "In conclusion, we observed an increased expression of PCAT14 in prostate cancer tissue." (PMID 35003397, 2021). "The results showed that PCAT14 was significantly overexpressed in prostate cancer." (PMID 35003397, 2021). "In addition, we analyzed the relationship between PCAT14 and immune-related pathways in prostate cancer by GSEA." (PMID 35003397, 2021). "In addition, PCAT14 probably influences the infiltration of immune cells through chemokines, antimicrobials, and cytokines, thus promoting prostate cancer development." (PMID 35003397, 2021).
prostate carcinoma (continued). "In addition, we attempted to explore the correlation between PCAT14 and immune cell infiltration in the prostate cancer tumor microenvironment and analyzed the immunological pathways closely related to prostate cancer." (PMID 35003397, 2021). "PCAT14 might promote the development of prostate cancer through chemokines, antimicrobials, and cytokines that affect the infiltration of immune cells." (PMID 35003397, 2021). "In addition, the ROC curve analysis showed that PCAT14 could be a biomarker for diagnosing prostate cancer." (PMID 35003397, 2021). "Moreover, due to the cancer- and lineage-specific expression pattern of lncRNAs, a group of lncRNAs have proven to be prospective biomarkers, e.g., PCA3 and PCAT14 in prostate cancer, which could be used for the early detection, diagnosis, and follow-up in the clinic." (PMID 34322486, 2021). "A lncRNA gene, PCAT14, plays an important role in tumorigenesis in HCC and prostate cancer." (PMID 36617651, 2022). "We also observed a negative correlation between PCAT14 expression and the infiltration level of Tregs in prostate cancer." (PMID 35003397, 2021). "The infiltration of immune cells in prostate cancer showed a significant negative correlation between the expression of PCAT14 and plasmacytoid dendritic cells, activated dendritic cells, regulatory T cells, and neutrophils." (PMID 35003397, 2021). "While, a novel prostate cancer and lineage-specific LncRNA PCAT14, which is transcriptionally regulated by AR, is overexpressed in low grade disease and lack of PCAT14 predicts for disease aggressiveness and recurrence in PCa." (PMID 28915709, 2017). "Eight studies assessed the relationship between lncRNA expression levels and biochemical recurrence-free survival (BRFS), whereas 2 studies investigated the relationship between the lncRNA PCAT14 and overall survival (OS), metastasis-free survival (MFS), and prostate cancer-specific survival (PCSS)." (PMID 29390487, 2017). "PCAT14, a new potential diagnostic marker for prostate cancer, could make up for the nonincreased PSA levels in diagnosing prostate cancer." (PMID 35003397, 2021).
hepatocellular carcinoma (4 papers, 2017 to 2025). A malignant tumor that arises from hepatocytes. "Here we show that the lncRNA PCAT-14 is overexpressed in patients with hepatocellular carcinoma (HCC), and is associated with a poor prognosis after surgery." (PMID 28415780, 2017). "Since PCAT-14 promotes proliferation and invasion, in addition to regulating the cell cycle, in hepatocellular carcinoma cells, it has been proposed as a novel prognostic factor and therapeutic target." (PMID 31319040, 2020).
metastatic disease (3 papers, 2017 to 2022). "PCAT14 expression is also an important prognostic for predicting metastatic disease." (PMID 36617651, 2022). "PCAT14 lower expression is significantly prognostic for multiple clinical endpoints supporting its significance for predicting metastatic disease that could be used to improve patient management." (PMID 33292248, 2020).
breast carcinoma (1 paper, 2020). "According to our data, PCAT-1 and PCAT-14, which were decreased as a result of CCT137690 treatment in breast cancer cells, may play a role in the anti-proliferative effects of CCT137690 on breast cancer cells." (PMID 31319040, 2020).
Brugada syndrome (1 paper, 2022). A genetically heterogeneous condition characterized by complete or incomplete right bundle branch block accompanied by ST elevation in leads V1-V3. "Two (NBPF gene and PCAT14 lncRNA) of these breakpoints have a reasonable potential to be key pathogenesis features of Brugada syndrome." (PMID 36617651, 2022). "Thus, the breakpoint at the PCAT14 gene is potentially involved with the Brugada syndrome pathogenesis." (PMID 36617651, 2022).
cancer (8 papers, 2017 to 2024). A tumor composed of atypical neoplastic, often pleomorphic cells that invade other tissues. "Three genes, AMACR (ENSG00000242110), PCAT14 ((ENSG00000280623) prostate cancer-associated transcript 14), and LTF (lactotransferrin) are frequently compared in studies of prostate data." (PMID 36360315, 2022). "PCAT-14 is a strong prognostic biomarker, and its expression increases significantly during the initial formation of cancer." (PMID 29755696, 2018). "Notably, both HOTAIRM1 and PCAT14 were confirmed as the critical regulators in cancer by multiple previous studies, but less is known about their regulatory roles during hESC development." (PMID 36907881, 2023). "To investigate the relationship between PCAT-14 and miR-372 in HCC, we evaluated the expression of miR-372 in three HCC cancer cell lines (SMMC7721, HepG2, and HCCLM3) transfected with either pcDNA-PCAT-14 or si-PCAT-14." (PMID 28415780, 2017). "They include PCAT-1, PCAT-6, PCAT-14, and PCAT-29, which play critical roles in the progression of several cancer types." (PMID 28415780, 2017). "However, PCAT14 may be a diagnostic and prognostic biomarker, since it is highly expressed in non-malignant tumor tissues, while the absence of PCAT14 promotes proliferation and recurrence of cancer." (PMID 34977151, 2021).
tumor (4 papers, 2017 to 2023). "In addition, the increased PCAT-14 expression was associated with tumor metastasis (P = 0.022) and larger tumor size (P = 0.006)." (PMID 28415780, 2017). "The tumor weight in mice injected with HepG2 cells transfected with si-PCAT-14 was lower than in the control si-NC group (0.48 ± 0.12g vs. 1.29 ± 0.19g, P < 0.01)." (PMID 28415780, 2017). "Up-regulation of lncRNA PCAT14 can impede tumor cell proliferation." (PMID 37253635, 2023). "Our results demonstrate that the PCAT-14 expression is associated with HCC metastasis, tumor size, and TNM stage, suggesting that PCAT-14 may be involved in the tumorigenesis and progression of HCC." (PMID 28415780, 2017).
PCAT14 also shares sentences with these, for which no sentence is quoted: prostate tumors (2 papers).